MIR3173 (microRNA 3173)
Synonyms: hsa-mir-3173; mir-3173
Gene: MicroRNA gene on chromosome 14 (95,137,919 to 95,137,986, reverse strand). Ensembl gene ENSG00000264607.
Homologues: Orthologues: chimpanzee MIR3173 (100% identical).
Diseases named in the same sentence as MIR3173 in open-access papers:
MIR3173 is named in the same sentence as 1 disease in open-access papers, as found by Europe PMC text mining. Sharing a sentence is not in itself a finding about the gene and the disease.
MIR3173 shares sentences with these, for which no sentence is quoted: lung disease (1 paper).